ENSG00000212558
Synonyms: LOC124900536
Gene: Small nucleolar RNA gene on chromosome 2 (10,090,205 to 10,090,319, reverse strand). Ensembl gene ENSG00000212558.
Gene Ontology:
Biological process: RNA processing
Cellular component: nucleolus
Homologues: Paralogues in human: SNORA26 (90% identical).